ENSG00000274491
Gene: Miscellaneous RNA gene on chromosome 20 (58,850,530 to 58,850,641, forward strand). Ensembl gene ENSG00000274491.
Homologues: Orthologues: mouse Gm56458 (74% identical).